AGT (angiotensinogen)
Diseases named in the same sentence as AGT in open-access papers (continued):
Sharing a sentence is not in itself a finding about the gene and the disease.
tumor (continued). "With the knowledge that the GG-genotype is related to decreased plasmatic AGT levels, and that AGT owns a physiological antiangiogenic activity, we infer that the GG-genotype might contribute to a proangiogenic tumor environment, and therefore, to more aggressive behavior and worse outcomes." (PMID 30383794, 2018). "Hence, the downregulation of AGT might decrease the serpine-mediated antiangiogenic activity of AGT, and consequently, contribute to a proangiogenic tumor microenvironment." (PMID 30383794, 2018). "An AGT/TGM2-expressing fibroblast subset is present in both healthy and tumor tissues, suggesting alternative trajectories to the classical NAF-to-CAF transition model." (PMID 42050076, 2026). "Specifically, FN1 (Log2 FC = 6.2), UGT1A1 (Log2 FC = 6.1), AGT (Log2 FC = 3.31), and COMT (Log2 FC = 2.4) were significantly upregulated in tumor tissues compared to normal tissues." (PMID 40564071, 2025). "Subsequently, we analyzed DEGs between tumor and normal tissues and selected the top five DEGs with the highest expression, which were SPP1, AKR1C2, AKR1B10, AGT, and EPHX1 in tumor tissues and NKG7, KLRD1, KLRB1, CCL5, and CST7 in normal tissues." (PMID 35967424, 2022). "Among these 9 candidate targets, AGT, DRD2, IL-1B, and IL-6 were significantly increased in primary tumor compared with the normal tissues, while ALB, IL-10, and IGF1 were significantly decreased in COAD tissues." (PMID 35280511, 2022). "The relative expression of genes of the RAS and RAS-related enzymes varied considerably in tumor tissue (–4, and S1, S2), with the prorenin receptor having the highest expression followed by prolyl endopeptidase, ACE2, and angiotensinogen." (PMID 34285715, 2021). "In tumor tissue, AGTR2 and MAS1 were weakly expressed; in contrast, ACE and AGT presented broad expression across 33 cancer types." (PMID 34671200, 2021). "We demonstrated expression of angiotensinogen by CSCs within the TNs, PRR, and AT2R by the CSCs within the TNs and the PTS, in addition to ACE on the endothelium of tumor microvessels in mHNcSCC." (PMID 33513805, 2021). "With regards to the clinical analysis of ccRCC samples from microarrays of GSE66272 and GSE73731, the upregulation of L1CAM and FBN1 and downregulation of AUTS2, MAPT, AGT and USH1C were observed along with an increase in tumor grade." (PMID 29215599, 2017). "We found that the expression levels of two upregulated genes (L1CAM and FBN1) were also increased along with tumor grade and that the expression levels of four downregulated genes (AUTS2, MAPT, AGT and USH1C) were decreased along with tumor grade." (PMID 29215599, 2017). "CX3CL1, AGT, ATP1A2, and IGSF1 mRNAs proved to be significantly down-modulated in the BM-infiltrating GD2 positive fractions compared to primary tumor cells (P<0.0001, P = 0.0325, P = 0.0196, P = 0.0047, respectively)." (PMID 22253825, 2012). "Compared to primary tumor cells, BM-infiltrating NB cells down-modulated the expression of CX3CL1, AGT, ATP1A2 mRNAs, whereas they up-regulated several genes commonly expressed by various lineages of BM resident cells." (PMID 22253825, 2012). "Key components of the RAS, namely angiotensinogen, ACE, ACE2, AT1R, AT2R, and the MasR were expressed in the sham liver, tumor-induced liver, and in CRC liver metastases (tumors) at all stages examined." (PMID 20380732, 2010). "The sensitivity of tumor cell lines to temozolomide and the alkylating agents BCNU and DTIC can be correlated with AGT levels." (PMID 19384285, 2009). "We demonstrated that tumor cells in hypoxic microenvironments produced AngII by a hypoxia-lactate-chymase-dependent mechanism, which is different from the classical AGT-renin-ACE-AngII pathway." (PMID 30208943, 2018). "In addition, tumors formed by AGT-silenced CNE2 and 5–8F cells displayed consistently reduced tumor volumes after irradiation with 10 Gy, as compared with those formed by cells treated with a negative control shRNA vector." (PMID 28205588, 2017).
tumor (continued). "Furthermore,network analysis showed that predictive genes are linked to the activity ofimportant secreted factors, which have the potential to influence tumor biology,such as IL1, IGF1, PDGF BB, AGT, and TGFβ." (PMID 21479216, 2011). "The production of renin and AGT or a potential function of renin, angiotensins and/or AGT in these tumours was not evaluated in these previous experiments." (PMID 14997208, 2004). "Since the expression of AGTR1 in BRCA and AGT in LAML/LGG was related to the DNA methylation level, DNA methyltransferases might be critically involved in the DNA methylation process during tumor development and progression." (PMID 34671200, 2021). "This approach could lead to the selective depletion of AGT in tumour tissue without corresponding depletion in normal tissue leading to sensitisation of tumours to O6 guanine targeting cytotoxic drugs such as temozolomide." (PMID 26811177, 2016). "In line with the acknowledged anti-tumor role of AGT, here we demonstrated that AGT was subjected to negative regulation by glucose concentration, and supplementation with ectopic expression of AGT significantly abrogated pro-tumor effects imposed by high glucose." (PMID 31142626, 2019). "The expression of AT1R, ACE, AGT, glutamine synthetase, CD44 and Fzd7 were not significantly changed in the tumor tissues from the captopril treated mice compared to control mice (respectively)." (PMID 34073112, 2021). "Similar to ATR blockage, AGT silencing did not influence cell proliferation in vitro as detected by MTT assay and tumor growth in our immunodeficient mouse model (NOD/SCID mice)." (PMID 30208943, 2018). "ACE, AT1R, MasR, and angiotensinogen were differentially expressed in control CRC liver metastases compared to the naïve (non-tumor bearing) and the tumor-bearing liver." (PMID 20380732, 2010). "mRNA of angiotensinogen, the precursor protein of AngII, ACE, and the AT1 receptor could be detected in HNSCC regardless of where the tumor originated." (PMID 35409002, 2022).
renal disease (222 papers, 2006 to 2026). "Our studies demonstrated that the hydrogen-peroxide-based stimulation of renal mesangial cells increases AGT expression and secretion, indicating AGT as an important molecule in kidney disease." (PMID 40003909, 2025). "Kidney AGT expression is increased in several DKD animal models, where AGT is induced by angiotensin II and promotes progression of kidney disease." (PMID 24793984, 2014). "Previous studies in humans suggested RAS components, such as urinary angiotensinogen, for the determination of kidney disease in diabetic as well as CKD patients." (PMID 23646149, 2013). "In a kidney-specific angiotensinogen knockout mouse model, the presence of liver-derived angiotensinogen suggested that the mechanism of kidney disease was due to the primary source of renal angiotensinogen protein and angiotensin II." (PMID 23844114, 2013). "Our finding of increased AGT transcription in cats with surgically induced CKD suggests that urinary angiotensinogen could be a valid biomarker for kidney diseases in cats, as well." (PMID 40560995, 2025). "This could be due to the fact that urinary AGT levels are highly sensitive to the onset of nephropathy." (PMID 40003909, 2025). "Here we discuss the potential benefits of selectively deleting liver-derived AGT for cardiovascular and kidney diseases and consider the side effects which may limit its broad therapeutic application." (PMID 35904033, 2022). "Estrogen also stimulates both the renin–angiotensin system and angiotensinogen that may exert specific deleterious effect on progression of renal disease." (PMID 31585527, 2019). "Estrogen also activates both the renin-angiotensin system and angiotensinogen that may exert specific deleterious effect on progression of renal disease." (PMID 31585527, 2019). "Although each segment has different functions, the level and localization of the expression of AGT mRNA and protein in each segment, and the role that changes in the expression of AGT may play in the development of kidney diseases remain unclear." (PMID 22606032, 2012). "Urinary angiotensinogen has been proposed as a promising candidate and is now increasingly used as a marker of intrarenal RAS activation in studies of people with kidney diseases." (PMID 40560995, 2025). "The three remaining RAAS genes included in this meta-analysis, ACE2, AGTR2 and REN, have not been researched as extensively as ACE, AGT and AGTR1 for associations with renal disease." (PMID 31048445, 2019). "Among RAAS candidate genes, angiotensinogen (AGT), angiotensin II type I receptor (AGTR1), angiotensin-converting enzyme (ACE), and aldosterone synthase (CYP11B2) genes appear to be particularly relevant to renal disease." (PMID 24977181, 2014).
cancer (165 papers, 2005 to 2026). A tumor composed of atypical neoplastic, often pleomorphic cells that invade other tissues. "We assessed the relationship between AGT gene M235T polymorphism and the susceptibility to cancer by performing an updated meta-analysis." (PMID 35317386, 2022). "This updated meta-analysis was carried out for assessing the relationship of AGT M235T polymorphism with the susceptibility to cancer." (PMID 35317386, 2022). "The aim of the present study was to compile case-control research and updated meta-analyses to explore the association between AGT M235T polymorphism and susceptibility for cancer, so as to more accurately assess the cancer risk." (PMID 35317386, 2022). "Variant expression of ACE, ACE2, and AGT was correlated with corresponding E3 ligase expression in cancer." (PMID 34671200, 2021). "However, accumulating evidence has shown that the function of AGT is closely associated with cancer." (PMID 40836964, 2025). "Firstly, the connection of AGT M235T polymorphism with cancer risk may be influenced by genetic relationships." (PMID 35317386, 2022). "AGT A-20C polymorphism is reported previously to predict a higher susceptibility to cancer." (PMID 35317386, 2022). "Angiotensinogen (AGT) was characterized as a risk factor in many cancers." (PMID 35280511, 2022). "However, most existing case-control studies are conducted to examine the relationship of AGT M235T polymorphism with the susceptibility to cancer." (PMID 35317386, 2022). "A possible explanation is that the stronger inhibitory effect of ACEIs compared with ARBs on angiotensinogen may be associated with cancer risk." (PMID 33587043, 2021). "So, the association of AGT with cancer risk has still been inconsistent." (PMID 32090070, 2020). "The mechanism through which the AGT gene influences cancer behavior might stem from genetic variants, bioactive peptides, enzymes, and receptors that have been recently summed to the RAS network." (PMID 30383794, 2018). "It was found that the functions of AGT was markedly related to the initiation and progression of cancer, due to that the transgenic mice with high levels of AGT are found to be at lower risk of developing cancer." (PMID 29221188, 2017). "In EC, AGT overexpression was associated with the anti-angiogenic effect of RAS, while high levels of AT1R was associated with cancer growth and progression." (PMID 34539580, 2021). "We describe how this K-Ras/AGT/Ang II pathway induces senescence in normal cells while fuels cell transformation in cancer cells through the differential coupling of the AT1-R to NOX2 and STAT3 signaling, respectively." (PMID 33380422, 2021). "Despite augmented expression in stage I and III cancers, AGT was decreased in stage II and IV cancers." (PMID 34671200, 2021). "In this study, we also investigated the functional significance of the oncogenic K-Ras–induced AGT activation and Ang II synthesis in both normal and cancer cells." (PMID 33380422, 2021). "In this study, we comprehensively integrated and analyzed the molecular characteristics of 6 significant members of the RAS family across pan-cancer: AGT, ACE, ACE2, AGTR1, AGTR2, and MAS1." (PMID 34671200, 2021). "Of note is AGT, encoding for the angiotensinogen, a component of the renin-angiotensin system (RAS), responsible for the final activation of angiotensin-converting enzymes (ACEs) and that has been shown to be involved in cancer biology and progression." (PMID 37041632, 2023). "According to previous meta-analysis, the M235T variant in the AGT gene is not related to the susceptibility to cancer." (PMID 35317386, 2022). "The upregulated DEPs associated with pathways in cancer were IKBKB, AGT, and PLCG2." (PMID 35334492, 2022). "Upregulated AGT expression in KIRC cancer cells could be confounded by the tissue-specificity of its expression in the kidney compared to other organs." (PMID 35079698, 2021).
cancer (continued). "Notably, the VEGFA, APLN, and AGT genes were more positively expressed in KIRC cancer cells (qVEGFA=1.7×10−4, qAPLN=1.4×10−13, qAGT=6.1×10−7), and showed substantial regulatory effects on downstream genes of the stroma (q." (PMID 35079698, 2021). "Therefore, we predicted VEGFA, APLN, and AGT genes as paracrine effectors for the cancer-stroma interaction in KIRCs, whereas DLL4, APP, and TGFB1 genes to be potential autocrine effectors." (PMID 35079698, 2021). "The role of angiotensinogen has not been clearly characterized in cancer; however, genetic polymorphisms are associated with gastric and lung cancer, but not OCSCC." (PMID 33513805, 2021). "Such stimulatory signals of AGT activation include the pro‐inflammatory cytokine interleukin‐6 and glucocorticosteroids, which both have been reported to predict poor outcome in bevacizumab‐treated cancer patients." (PMID 32133779, 2020). "According to findings in the present meta-analysis, AGT M235T polymorphism may not be related to cancer susceptibility." (PMID 35317386, 2022). "For instance, cathepsins can directly convert angiotensinogen to angiotensin II, which then binds to AT1R and promotes cancer progression." (PMID 39684895, 2024). "The oncoprint displayed an overall alteration frequency of RAS family of 15.2% in TCGA pan-cancer across TCGA cancers, with the highest frequency existing for ACE (4%), followed by AGT (3%), AGTR1 (3%), ACE2 (2.3%), AGTR2 (1.5%) and MAS1 (1.4%)." (PMID 34671200, 2021). "We found that TMPRSS2, SLC6A19, ATGR2, AGT, ACE2, and ACE1 had >5% CNV amplification or deletion in 33 cancers." (PMID 34458283, 2021). "Interestingly, the relative expression levels of estimated paracrine effectors, such as VEGFA, APLN, and AGT, were found to be strikingly and significantly higher in PDX cancer components than in cell lines obtained from CCLE data." (PMID 35079698, 2021). "The liver may be a fertile ground for CRC metastasis due to its production of AGT, which CRC metastases could utilize via elevated levels of ACE to produce more ATII and drive cancer growth via AT1R-mediated mechanisms." (PMID 34428252, 2021). "However, it does not necessarily deny the possible role of AGT in cancer-stroma interactions." (PMID 35079698, 2021).
infection (128 papers, 2008 to 2026). The state of being infected such as from the introduction of a foreign agent such as serum, vaccine, antigenic substance or organism. "Following infection with dengue virus, there is up regulation of angiotensinogen and the high plasma levels of angiotensin II impair endothelial cell function and induce apoptosis of endothelial cells." (PMID 32609737, 2020). "Changes in mRNA expression levels of endothelial-like cells following infection with dengue virus type 2 showed the up regulation of angiotensinogen and the high plasma levels of angiotensin II impair endothelial cell (EC) function, inhibit EC motility and induce apoptosis of human ECs." (PMID 26895439, 2016). "Fifth, the serum levels of ACE, angiotensinogen, angiotensin 1–7, chymase, and the other enzymes of the renin-angiotensin system were not measured in the patients of this cohort, and thus their associations with the risk of infection were not evaluated." (PMID 35155493, 2022). "When inspecting the quantitative data for other proteins in the renin-angiotensin system, two other proteins were found to be down-regulated 24 h post-infection, namely cathepsin A (CTSA) and angiotensinogen (AGT)." (PMID 32575076, 2020). "At this time, MET vaccinated fish showed an increase in hemostasis-related proteins (e.g., angiotensinogen, fibrinogen C-terminal domain-containing protein and alpha-2-macroglobulin-like), whereas CTRL vaccinated fish displayed a response more akin to pre-infection groups." (PMID 41256851, 2025).
heart disease (76 papers, 2009 to 2025). "Under dominant model, the significant AF risk was observed in AGT SNP7 rs3789678, compared with the non-AF heart disease control group (P = 6.40E-03, OR = 1.573, 95% CI = 1.246–1.986 for CT+TT vs.CC)." (PMID 25723521, 2015). "Genotype distribution of 10 genotyped SNPs of AGT, CYP11B2andACE genes between AF group and non-AF heart disease control/healthy control group." (PMID 25723521, 2015). "After Bonferroni correction (the results were corrected for SNP number and the number of statistical analyses), the allele frequencies of AGT gene SNP5 rs11568023 was significantly different between the AF group and non-AF heart disease control group (P = 0.0003)." (PMID 25723521, 2015).
metabolic disorders (28 papers, 2014 to 2025). "In this work, we present the first report on the consequences of site-specific phosphorylation in human AGT, a metabolic enzyme whose deficit leads to PH1, a monogenic metabolic disease caused by mutations affecting protein stability and trafficking." (PMID 36557898, 2022). "Previous studies focused on the vasoconstrictor arm of the RAS (ACE/AngII/AT1R) in rodents, illustrating that females are protected from cardiovascular and metabolic disorders produced by AGT, renin, and angiotensin II, as compared to males." (PMID 35629915, 2022). "Collectively, the current study highlights the pivotal role of hepatocyte-specific AGT in metabolic disorders." (PMID 31604805, 2019). "Differential expression of AGT and CTSD in Homc cells between OA samples and normal samples might indicate that the development and metabolic disorder of chondrocytes are involved in the progress of OA23,which is consistent with our results." (PMID 37853066, 2023).
retinopathy (15 papers, 2011 to 2025). "Though the significant difference was found about M/T allele in our outcome, multiply complicated risk factors should be considered when illustrated the relationship between AGT polymorphism and Chinese T1DM patients with retinopathy." (PMID 29484134, 2018). "In fact, 155 patients (54 with DR, 101 with diabetic non-retinopathy, DNR) were determined with ACE genotypes and 133 (48 with DR, 85 with DNR) with AGT genotypes due to the loss of blood samples." (PMID 29484134, 2018). "Beyond of above factors, genetic gene polymorphisms obtained more attentions about the pathophysiological process leading to proliferative retinopathy in recent studies, such as ACE I/D, AGT M/T gene." (PMID 29484134, 2018). "In this study, we reported that the relationship between ACE, AGT gene polymorphism and T1DM subjects with retinopathy was not significant and the results were still consistent after adjusting for confounding factors." (PMID 29484134, 2018). "By comparing vitreous samples from patients with PDR, diabetic patients without retinopathy and non-diabetic patients, the study found that angiotensinogen was upregulated in PDR compared to samples from diabetic patients without retinopathy and non-diabetic patients." (PMID 28452939, 2017).